NMU (neuromedin U)
Description:
[Neuromedin-U-25]: Multifunctional neuropeptide that acts via two G protein-coupled receptors, NMUR1 and NMUR2. Functionally, is involved in pleiotropic roles, including regulation of feeding, energy balance, blood pressure and smooth muscle contraction (By similarity). Additionally modulates hormone release and inflammatory responses in a tissue- and receptor-dependent manner. Mechanistically, binding to NMUR1 or NMUR2 results in coupling of receptors to Galpha proteins, namely GNAQ/Gaq or GNA11/Ga11 and GNAI1/Gai subunits. GNAQ/Gaq or GNA11/Ga11 coupling leads to the activation of a phospholipase C (PLC), which hydrolyzes PIP2 (phosphatidylinositol 4,5-bisphosphate) into DAG (diacylglycerol) and IP3 (inositol trisphosphate), and subsequent intracellular calcium mobilization via IP3 receptors on the endoplasmic reticulum. GNAI1/Gai coupling inhibits forskolin-stimulated cAMP accumulation. In pancreatic beta cells, regulates insulin secretion through NMUR1 coupled to GNAI2 and GNAO1, resulting in reduced intracellular Ca2+ influx and cAMP levels. Through NMUR1 in Th2-type T cells, enhances type 2 cytokine secretion and modulates inflammatory responses via activation of PLC-calcineurin-MEK and PI3K signaling pathways. [Neuromedin precursor-related peptide 33]: Does not function as a ligand for either NMUR1 or NMUR2. Indirectly induces prolactin release although its potency is much lower than that of neuromedin precursor-related peptide 36. [Neuromedin precursor-related peptide 36]: Does not function as a ligand for either NMUR1 or NMUR2. Indirectly induces prolactin release from lactotroph cells in the pituitary gland, probably via the hypothalamic dopaminergic system.
Tractability: Antibody: its Gene Ontology location is reachable by antibodies, with high confidence; UniProt places it where antibodies can reach, with medium confidence; UniProt predicts a signal peptide or a membrane-spanning region.
Gene: Protein-coding gene on chromosome 4 (55,595,229 to 55,636,747, reverse strand). Ensembl gene ENSG00000109255.
Subcellular location: Secreted (Neuromedin-U-25)
Pathways (Reactome):
Signal Transduction: G alpha (i) signalling events; G alpha (q) signalling events; Peptide ligand-binding receptors
Gene Ontology:
Molecular function: protein binding; type 1 neuromedin U receptor binding; type 2 neuromedin U receptor binding; neuromedin U receptor binding; signaling receptor binding
Biological process: neuropeptide signaling pathway; G protein-coupled receptor signaling pathway; positive regulation of smooth muscle contraction; positive regulation of synaptic transmission; eating behavior; energy homeostasis; gastric acid secretion; negative regulation of eating behavior; negative regulation of feeding behavior; negative regulation of gastric acid secretion; negative regulation of gastric emptying; photoperiodism; positive regulation of cytosolic calcium ion concentration; positive regulation of heart rate; positive regulation of heat generation; positive regulation of hormone secretion; positive regulation of prolactin secretion; positive regulation of sensory perception of pain; positive regulation of stomach fundus smooth muscle contraction; positive regulation of systemic arterial blood pressure; regulation of circadian sleep/wake cycle, sleep; regulation of feeding behavior; regulation of grooming behavior; regulation of smooth muscle contraction; temperature homeostasis
Cellular component: extracellular region; terminal bouton
Genetic constraint (gnomAD): Loss-of-function variants: 4 observed, 7.1 expected, observed/expected ratio (o/e) 0.56, 90% interval 0.28 to 1.28. That is too few expected variants to judge how well the gene tolerates losing a copy. Missense variants: 87 observed, 68 expected, observed/expected ratio (o/e) 1.28, 90% interval 1.08 to 1.53. Synonymous variants: 36 observed, 30.67 expected, observed/expected ratio (o/e) 1.17, 90% interval 0.9 to 1.55.
Homologues: Orthologues: chimpanzee NMU (99% identical), macaque NMU (93% identical), guinea pig NMU (75% identical), mouse Nmu (74% identical), pig NMU (74% identical), dog NMU (72% identical), rat Nmu (71% identical), rabbit NMU (71% identical), tropical clawed frog nmu (56% identical), zebrafish nmu (41% identical).
Diseases named in the same sentence as NMU in open-access papers:
NMU is named in the same sentence as 44 diseases in open-access papers, as found by Europe PMC text mining. Sharing a sentence is not in itself a finding about the gene and the disease. The quoted sentences say what the papers report.
Obesity (10 papers, 2017 to 2025). Accumulation of substantial excess body fat. "One of these neuropeptides, Neuromedin U (NMU), is an anorexigenic factor and is expected to be a potential target for anti-obesity agents." (PMID 36302800, 2022). "As the gene with the second highest correlation with thyroid cancer in our study, neuromedin U (NMU), a neuropeptide originally isolated from the spinal cord of pigs, has multiple physiological functions and is involved in obesity and inflammation." (PMID 32337286, 2020). "Neuromedin U (NMU) is a hypothalamic neuropeptide with important roles in several metabolic processes, recently suggested as potential therapeutic target for obesity." (PMID 28235053, 2017). "A further investigation to analyze NMU/NMUR1 pathway in MC may provide a link between obesity and KOA pathology." (PMID 36232539, 2022). "Studies in genetically modified mice establish that essential roles of endogenous neuromedin U (NMU) are anorexigenic function and metabolic regulation, indicating that NMU is expected to be a potential target for anti-obesity agents." (PMID 36302800, 2022). "We quantified expression of chromogranin A, glucagon‐like peptide‐1 (GLP‐1), serotonin, and neuromedin U (NmU) in duodenal biopsies from 34 participants with obesity (19 with T2D, 15 without) and six healthy controls." (PMID 40790227, 2025). "Neuromedin U (NMU), a secreted neuropeptide belonging to the neuromedin family, was originally isolated from porcine spinal cord and has been related to multiple physiological functions involved in stress, immune response, obesity, and energy metabolism." (PMID 31575084, 2019).
lung carcinoma (5 papers, 2015 to 2022). "Analyzing the mRNA expression microarrays showed FOS, GTSE1, CDKN1C, and NMU are greatly harbored by the patients of lung cancer and are observed to be differentially expressed (fold change ≥2.0) of these genes." (PMID 32318583, 2020). "Western blot analysis confirmed the increased expression of NMU protein in lung cancer tissue, and the results were consistent with RT-PCR data." (PMID 31492042, 2019). "For example, the NMU gene is specifically up-regulated in non-small cell lung cancers, whereas depletion of NMU expression inhibits the growth of the lung cancer cells." (PMID 26317338, 2015). "The experimental results show that CEP55, NMU, CAV1, TBX3, FBLN1and SYNM have significantly different expression in lung cancer." (PMID 36404510, 2022). "We strongly believe that GTSE1, NMU, FOS, and CDKN1C have potential and clinical application values to act as prognostic markers of lung cancer." (PMID 32318583, 2020). "After screening 952 CDEGs, we found that the up-regulation of neuromedin U (NMU) and GTSE1 in the case of lung cancer is related to poor prognosis." (PMID 32318583, 2020). "Based on our results, we found potential and prospective clinical applications in GTSE1, NMU, FOS, and CDKN1C to act as prognostic markers in case of lung cancer." (PMID 32318583, 2020). "The demonstration of the potential medical value of GTSE1, NMU, FOS, and CDKN1C in the prognosis of patients suffering from lung cancer was done by us in order to verify the levels of expression of FOS, CDKN1C, NMU, and GTSE1." (PMID 32318583, 2020). "The analysis of lung cancer tissue samples from non-small-cell lung carcinoma (NSCLC, stage I to III) and small-cell lung carcinoma (SCLC, stage IV) showed NMU overexpression compared to normal lung tissue." (PMID 31492042, 2019). "Additionally, CDKN1C, GTSE1, NMU, and FOS are not correlated with one another, which indicates that every target can individually be cast off as a predictive marker for lung cancer." (PMID 32318583, 2020).
pancreatic cancer (5 papers, 2016 to 2021). "The MIA PaCa-2 cell line, which has the lowest expression levels of YAP1 and NMU among the pancreatic cancer cell lines tested, was chosen as an adequate in vitro tumor model." (PMID 31575084, 2019). "Analysis of different pancreatic cancer databases showed that Neuromedin U (NMU) expression was positively correlated with YAP1 expression in the tumor group." (PMID 31575084, 2019). "To determine the prognostic value of YAP1 and NMU expression in patients with pancreatic cancer, we compared the outcomes of patients with low expression (n = 87) and high expression (n = 87) of these proteins." (PMID 31575084, 2019). "We identified an association between NMU and YAP1 and provide in vivo and in vitro evidence supporting the essential role of NMU in YAP1-driven pancreatic cancer progression and metastasis." (PMID 31575084, 2019). "A tissue microarray (TMA) containing 66 pancreatic cancer samples showed marked variation in YAP1 and NMU expression." (PMID 31575084, 2019). "The co-expression of NMU and NMUR2, validated at the mRNA and protein levels, was also correlated with increased invasiveness and metastatic potential in pancreatic cancer cells (i.e., ASPC1, Capan1, Colo357, SU86.86, BxPC3, Capan1)." (PMID 31492042, 2019). "The data filtering narrowed the number of genes to a final list of four that had limited information on pancreatic cancer as well as immunosuppression: secreted phosphoprotein 1 (SPP1, osteopontin), granulin, trefoil factor 2 (TFF2), and neuromedin U (NMU)." (PMID 30533259, 2018). "The data filtering resulted in a final list of two genes that had little information on pancreatic cancer and immunosuppression: trefoil factor 2 (TFF2) and neuromedin U (NMU)." (PMID 30533259, 2018). "This is the first report showing that YAP1/TEAD directly regulate NMU, indicating that a YAP1/TEAD/NMU pathway may be important for YAP1-dependent tumor metastasis and the poor outcome of pancreatic cancer." (PMID 31575084, 2019). "The immunohistochemical staining showed neither NMU nor NMUR2 immunoreactivity in the normal pancreas, while in the pancreatic cancer tissues, there was very high cytoplasmic staining of NMU and NMUR2, which was also detected in the cell membrane." (PMID 31492042, 2019).
breast carcinoma (4 papers, 2017 to 2023). "However, in line with our mRNA data, these preliminary qualitative findings on protein level indicate an up-regulation of NMU protein in breast cancer cells compared to expression in associated normal breast epithelium." (PMID 28423716, 2017). "This kind of behavior is documented for humans, e.g., by NmU overexpression, a protein involved in breast cancer progression and metastization, or by an increased activity of the enzyme cytochrome P4503A4, leading to resistance to therapy." (PMID 33800900, 2021). "We demonstrated that NMU mRNA expression is significantly up-regulated in all molecular breast cancer subtypes (except for normal-like cases) compared to normal breast tissue controls." (PMID 28423716, 2017). "Moreover, we also provide first-time evidence that NMU protein is expressed in human breast cancer cells using immunohistochemistry and western blot analysis." (PMID 28423716, 2017). "At the same time, higher expression of 4 important genes (NMU, COL2A1, PRAME, and TTYH1) that contribute to higher breast cancer lung metastasis was observed in the tumors from Black women compared to the tumors from white women with an adjusted p-value of 0.000664734 (one-way ANOVA)." (PMID 36702853, 2023).
diabetes (4 papers, 2021 to 2025). "By activating two GPCRs, NMU1 and NMU2, NmU peptides are related to multiple pathophysiological roles in diabetes, metabolic disorder, inflammation, and cancer." (PMID 36575163, 2022).
endometrial cancer (4 papers, 2016 to 2025). Primary or metastatic malignant neoplasm involving the endometrium (mucous membrane that lines the endometrial cavity). "In the present study, we found that NMU and NMUR2 are co-expressed in the mouse normal uterine endometrium and also in human endometrial cancer tissue samples." (PMID 26849234, 2016).
endometrioid endometrial carcinoma (3 papers, 2018 to 2024). "It has been reported that HAND2-AS1 inhibits invasion and metastasis through activating neuromedin U in endometrioid endometrial carcinoma." (PMID 38956502, 2024).
hepatocellular carcinoma (3 papers, 2013 to 2021). A malignant tumor that arises from hepatocytes. "In a previous study, the level of the NMU protein was found to be elevated in hepatocellular carcinoma (HCC), and the prognosis of individuals with HCC with the elevated NMU expression was remarkably worse in contrast with that of individuals with low NMU expression." (PMID 34336003, 2021).
Arthritis (2 papers, 2012 to 2021). Inflammation of a joint. "We utilized Nmu gene knockout (NMU-KO) mice to investigate a potential role for NMU in the pathogenesis of autoantibody-mediated arthritis." (PMID 22314006, 2012).
head and neck squamous cell carcinoma (2 papers, 2019 to 2021). A squamous cell carcinoma that arises from any of the following anatomic sites: lip and oral cavity, nasal cavity, paranasal sinuses, pharynx, larynx, and salivary glands. "Interestingly, after initial reports implying the suppressive effects of NMU in oesophageal and head and neck squamous-cell carcinomas, many other studies demonstrated neuromedin U as a diagnostic and/or prognostic biomarker in various tumours." (PMID 31492042, 2019).
lung adenocarcinoma (2 papers, 2020 to 2021). A carcinoma that arises from the lung and is characterized by the presence of malignant glandular epithelial cells. "According to the qRT-PCR results, the mRNA expression of NMU was in most cases, overexpressed (3 times higher expression) in the lung adenocarcinoma cells than in nonmalignant lung cells." (PMID 34336003, 2021).
thyroid cancer (2 papers, 2019 to 2020). "Among the top 30 hub genes obtained in PPI network, the expression levels of FN1, NMU, CHRDL1, GNAI1, ITGA2, GNA14 and AVPR1A were associated with the prognosis of thyroid cancer." (PMID 32337286, 2020). "In addition, survival analysis showed that the high expression of FN1 and NMU genes significantly decreased DFS of patients with thyroid carcinoma." (PMID 30872410, 2019). "The Human Protein Atlas (HPA)-based Immunohistochemistry (IHC) database showed that FN1, NMU, and ITGA2 were upregulated in thyroid cancer tissues compared with normal tissues, while CHRDL1, GNAI1 and GNA14 were downregulated in thyroid cancer tissues." (PMID 32337286, 2020). "Hence, we derived seven key genes related to the prognosis of thyroid cancer: FN1, NMU, CHRDL1, GNAI1, ITGA2, GNA14, AVPR1A." (PMID 32337286, 2020).
Anxiety (1 paper, 2022). Intense feelings of nervousness, tension, or panic often arise in response to interpersonal stresses. "Several synthetic bioactive peptides related to urocortin 3, growth hormone-releasing hormone, neuromedin U, and kisspeptin, have antidepressant-like or anxiety-like effects via the receptors for neurotransmitters or the release of neurotransmitters." (PMID 35203663, 2022).
breast tumours (1 paper, 2019). "The immunohistochemical staining of breast tumours identified the NMU protein, but only in those tissues that showed very high expression of NMU mRNA." (PMID 31492042, 2019).
colon cancer (1 paper, 2019). "In our investigations of colon cancer cells (HT29), we found that NMU and NMUR2 are co-expressed in colon cancer cell lines with induced EMT." (PMID 31492042, 2019).
colorectal cancer (1 paper, 2022). A primary or metastatic malignant neoplasm that affects the colon or rectum. "Neuromedin U (NMU) was identified as one of the hub genes closely related to colorectal cancer (CRC) progression and was recently shown to be a motility inducer in CRC cells." (PMID 36482448, 2022).
endometriosis (1 paper, 2022). The growth of functional endometrial tissue in anatomic sites outside the uterine body. "ACKR1, LMNB1, MFAP4, NMU, and SEMA3C were upregulated in ectopic endometrial tissues of patients with endometriosis compared with normal endometrium (P < 0.001), which was consistent with the results of bioinformatics analysis." (PMID 36277723, 2022). "Q RT-PCR was used to detect the expression of ACKR1, LMNB1, MFAP4, NMU, and SEMA3C mRNA in ectopic endometrial tissues of patients with endometriosis." (PMID 36277723, 2022).
eosinophilia (1 paper, 2022). "Furthermore, NmU has been shown to promote airway eosinophilia in an allergic mouse model, as NmU-knockout attenuated the eosinophilic inflammation." (PMID 35810259, 2022).
heart failure (1 paper, 2026). Inability of the heart to pump blood at an adequate rate to meet tissue metabolic requirements. "Therefore, an investigation into whether the protein neuromedin U (NMU), which is significantly elevated in heart failure patients, mediates a classical diuresis that results from a sustained increase in left atrial pressure was conducted in the anaesthetized pig." (PMID 42102053, 2026).
hypophysis (1 paper, 2017). "The expression of NMU was observed in hypophysis and kidney, with a statistical difference found in hypophysis and kidney tissues between CHD and EUD, suggesting potential enhancer activities for the intron sequence." (PMID 28819228, 2017).
memory impairment (1 paper, 2020). "NMU encodes a member of the neuromedin family of neuropeptides, which play important roles in inflammation-mediated memory impairment and neuronal cell-death." (PMID 32854783, 2020).
nematode infection (1 paper, 2021). "These include the key discovery of the neuropeptide neuromedin U to act on type 2 innate lymphoid cells and regulate their function during nematode infection." (PMID 34571902, 2021).
oral squamous cell carcinoma (1 paper, 2019). "The first report that linked neuromedin U to cancer showed NMU was significantly downregulated in each of the five examined oral squamous cell carcinoma (OSCC) samples compared to healthy tissues." (PMID 31492042, 2019).
osteoarthritis (1 paper, 2022). A noninflammatory degenerative joint disease occurring chiefly in older persons, characterized by degeneration of the articular cartilage, hypertrophy of bone at the margins and changes in the synovial membrane. "Neuromedin U (NMU) and NMU receptors (NMUR1 and NMUR2) are associated with obesity-related disorders and found in mast cells (MCs), which are elevated in osteoarthritis." (PMID 36232539, 2022).
ovarian carcinoma (1 paper, 2015). A malignant neoplasm originating from the surface ovarian epithelium. "Taken together, up-regulation of both NMU and NMUR2 in ovarian cancers as shown by our findings suggests that over-activation of NMU signaling may be involved in promoting ovarian tumorigenesis." (PMID 26317338, 2015). "Following this, we further found the transcripts of NMU and NMUR2 are significantly induced in the ovarian cancer tissues; this increase was by 941 folds and 5 folds, respectively on average compared to those in the adjacent normal controls." (PMID 26317338, 2015). "Overexpression of NMUR2S significantly suppresses NMU downstream signaling and the proliferation rate of SKOV-3 ovarian cancer cell line, which expresses NMUR2 dominantly and NMUR1 moderately." (PMID 26317338, 2015). "Based on our previous finding that NMU signaling is present in the ovary, here we further have shown that both the transcript and protein levels of NMU and NMUR2 were increased in ovarian cancer tissue samples." (PMID 26317338, 2015).